CYP2F2P (cytochrome P450 family 2 subfamily F member 2, pseudogene)
Synonyms: formerly CYP2F1P
Gene: Transcribed processed pseudogene on chromosome 19 (40,818,721 to 40,826,772, reverse strand). Ensembl gene ENSG00000237118.
Diseases named in the same sentence as CYP2F2P in open-access papers:
CYP2F2P is named in the same sentence as 1 disease in open-access papers, as found by Europe PMC text mining. Sharing a sentence is not in itself a finding about the gene and the disease. The quoted sentences say what the papers report.
chronic obstructive pulmonary disease (1 paper, 2021). A chronic and progressive lung disorder characterized by the loss of elasticity of the bronchial tree and the air sacs, destruction of the air sacs wall, thickening of the bronchial wall, and mucous accumulation in the bronchial tree. "CYP2F2P is associated with the risk of chronic obstructive pulmonary disease." (PMID 33931030, 2021).